MIF (macrophage migration inhibitory factor)
Diseases named in the same sentence as MIF in open-access papers (continued):
Sharing a sentence is not in itself a finding about the gene and the disease.
kidney disease (continued). "However, in patients with SLE urinary MIF was also increased, but was not linked to active renal disease, therefore the role of MIF is unclear." (PMID 35091838, 2022). "However, there was no clear association between the MIF genotype and type of kidney disease in ESRD." (PMID 26858715, 2016). "MIF is also elevated in both the kidney tissue and urine in kidney diseases and activation of CD74 by MIF leads to an inflammatory response in podocytes." (PMID 33321755, 2020). "The production of MIF is increased in both immune and non-immune mediated kidney diseases, which promotes inflammation and kidney injury by the accumulation of macrophages and T-cells." (PMID 38534333, 2024). "However, we now show that the expression of CD74 and its ligands MIF and DDT was persistently increased suggesting that TWEAK is one of the drivers of their increased expression in kidney disease." (PMID 29924850, 2018). "However, no clinical trial for anti-MIF antibody treatment for kidney disease has been performed." (PMID 35563296, 2022).
infectious disease (23 papers, 2007 to 2025). A disorder directly resulting from the presence and activity of a microbial, viral, or parasitic agent in humans. "Although a protective role for MIF has been attributed in infectious diseases, uncontrolled MIF activity it has been implicated in several chronic inflammatory diseases including renal, rheumatic, metabolic and ocular." (PMID 37626184, 2023). "These therapeutic options hold great potential for use in the treatment of several infectious diseases and other MIF-associated pathologies and need to be further explored and developed." (PMID 38275363, 2023). "In the case of rs5844572, that is also localized in MIF promoter sequence, the pressure of continuous exposition to infectious diseases would explain the high prevalence of low-expression MIF alleles in Africa." (PMID 29545822, 2018). "Interindividual variations of circulating MIF levels have been analyzed in the context of MIF polymorphisms in patients with inflammatory, autoimmune, and infectious diseases." (PMID 28179905, 2017). "MIF polymorphisms and protein expression also have an impact on outcomes in patients with infectious diseases." (PMID 27014277, 2016). "In infectious diseases, MIF promotes pneumococcal clearance; however, MIF alleles that promote gene expression are associated with severe malarial anemia." (PMID 27014277, 2016). "In addition to therapeutic applications, MIF is also emerging as a promising diagnostic and prognostic tool for use in various infectious diseases." (PMID 38275363, 2023). "In addition, in patients admitted to a medical emergency department or a department of infectious diseases, we found that sTREM-1, MIF and suPAR as single markers have limited diagnostic power to discriminate between bacterial and nonbacterial causes of inflammation." (PMID 17362525, 2007). "Macrophage migration inhibitory factor (MIF) and its homolog, D-dopachrome tautomerase (D-DT), are cytokines that play critical roles in the immune response to various infectious diseases." (PMID 38275363, 2023). "The deeper we delve into the fascinating world of MIF and D-DT and their interaction with infectious diseases, the clearer it becomes that further research is needed to fully unravel the intricacies of these model cytokines." (PMID 38275363, 2023). "The tautomerase activity of MIF also plays a special role in the consideration of MIF in relation to infectious diseases." (PMID 38275363, 2023). "This duality highlights the complex interplay between MIF and the intricate immune mechanisms involved in infectious diseases and underscores the need for personalized approaches to therapeutic interventions targeting MIF-related pathways." (PMID 38275363, 2023). "Further research is needed to unravel the complexity of MIF and D-DT in infectious diseases and to develop personalized therapeutic approaches targeting these cytokines." (PMID 38275363, 2023). "MIF mediates host innate and adaptive immunity and regulates survival pathways, important for pathogen elimination during infectious disease." (PMID 35406551, 2022). "As the examination of MIF in chronic inflammation grew, it became a focus in infectious disease as well." (PMID 24887129, 2014). "Numerous hypotheses have been proposed to explain the complex and dual role of MIF in different infectious diseases." (PMID 38275363, 2023). "The MIF cytokine family exerts a special role in infectious diseases and inflammations." (PMID 38275363, 2023). "The use of MIF as a potential biomarker could revolutionize disease detection and monitoring in these infectious diseases." (PMID 38275363, 2023). "Collectively, the MIF and IL-10 dyad could be considered as a potential novel molecular Yin-Yang in infectious disease progression." (PMID 35464430, 2022). "Indeed, MIF has been shown to influence the pathogenesis of infectious diseases, participating in the protective immune response or playing a critical role in its immunopathogenesis." (PMID 22496958, 2012).
infectious disease (continued). "The essential role of MIF in the pathogenesis of infectious diseases and, consequently, the concept that it might be used as therapeutic target still require extensive clinical studies." (PMID 22496958, 2012). "In this context, the macrophage migration inhibitory factor (MIF) and the interleukin-10 (IL-10) cytokines may operate as a molecular “Yin-Yang” in the modulation of the host immune microenvironment during African trypanosome infection, and possibly other infectious diseases." (PMID 35464430, 2022). "In infectious disease controls, a similar pattern was observed, but without correlations between DLL1 and MIF and IL-10." (PMID 38502427, 2024).
inflammation (18 papers, 2008 to 2023). Aberrant reaction of the microcirculation characterized by movement of fluid and leukocytes from the blood into extravascular tissues. "The regulating function of IGF2BP1 in E2F1 and MIF expression during acute renal inflammation in vivo was then examined." (PMID 36632449, 2023). "Macrophage Migration Inhibitory Factor shows cardio-protective functions but provokes cardiac inflammation which in turn is known to be detrimental for the myocardial tissue after MI." (PMID 30678084, 2019). "Our data also suggests that MIF in serum is a potential biomarker bridge to identify children with CNS inflammation." (PMID 24133408, 2013). "Elevated MIF levels in CRS patients suggest its role in persistent sinus inflammation." (PMID 37745856, 2023). "Aging promoted cardiac inflammation, the effect was attenuated by MIF knockout." (PMID 26940544, 2016). "The relationship between increased MIF levels in patients with UTI-related renal inflammation and TLR4 is, therefore, speculative." (PMID 23319831, 2012). "Activation of urothelial PAR1 receptors, either by locally generated thrombin or proteases present in the urine, may mediate bladder inflammation by inducing urothelial MIF release and upregulating urothelial MIF expression." (PMID 21209875, 2010). "Therefore, all of the components are in place during bladder inflammation for MIF-activated signal transduction to occur." (PMID 19066630, 2008). "The results showed that HQJGD and HQHLD could alleviate pulmonary inflammation in UC-related lung injury by obviously improving the pathology and fibrosis of the lung, inhibiting the positive feedback loop of MIF/NF-κB, and reducing lymphocyte homing to bronchial mucosa." (PMID 35815289, 2022). "Uptake of EVs by Kupffer cells in the liver induced the TGF-β signaling pathway via activation of the macrophage migration inhibitory factor (MIF), a known mediator of liver inflammation and fibrosis." (PMID 35493080, 2022). "All these data indicated that AEE could prevent lung inflammation during ALI in rats by decreasing CRP, MPO, and MIF in a dose-dependent manner." (PMID 35967416, 2022). "MIF decreased but IL-8 increased at 1 week, suggesting neutrophils but not macrophages work effectively in acute colon inflammation." (PMID 35844499, 2022). "The role of MIF as a neuro-immune mediator linking inflammation with depressive symptoms and HPA dysregulation, and its concomitant increases in CSF and serum makes MIF a potential biomarker to identify children with systemic and CNS inflammation." (PMID 24133408, 2013).
metabolic disorders (18 papers, 2013 to 2025). "Moreover, despite the known involvement of MIF in inflammatory and metabolic disorders, its genetic influence via rs1007888 on GDM risk within the context of higher pre-BMI appears to be negligible or absent in our specific cohort." (PMID 41036138, 2025). "The causative link between MIF secretion and metabolic disorders has still to be demonstrated." (PMID 23536817, 2013). "At the pathway level, our observations are consistent with known pro-tumorigenic inflammatory mechanisms shared between metabolic disease and carcinogenesis, including IL-6, MIF, GALECTIN, and CXCL signaling." (PMID 41488617, 2025). "The administration of the MIF siRNA completely suppressed MIF expression and showed deteriorated performance of lipid accumulation and metabolism disorder." (PMID 36147562, 2022). "In metabolic disorders, MIF may be released from circulating monocytes and adipose tissue, leading to high plasma MIF levels." (PMID 37935315, 2024). "Furthermore, IF treatment mitigates metabolic disorders in the livers of HFD mice by activating MIF signaling." (PMID 37567977, 2023). "Macrophage migration inhibitory factor (MIF) is a pleiotropic cytokine involved in the regulation of innate and adaptive immunity and higher levels of MIF were found in metabolic disease." (PMID 38531873, 2024). "The group (MD+/OW) was also characterized with higher levels of CRP, leptin, MDA, IL-18, MIF (p < 0.05), when compared to overweight patients with PCOS in the absence of metabolic disorders (MD−/NW)." (PMID 32397375, 2020).
bacterial infection (16 papers, 2007 to 2023). "MIF is a key molecule closely associated with bacterial infection and the subsequent immune response." (PMID 37919720, 2023). "For instance, bacterial infections, including the most severe endotoxin shock cases, are associated with the high MIF concentrations produced by macrophages during immune cell-mediated bacterial clearance." (PMID 36329091, 2022). "Our experiments have uncovered that mice deficient for macrophage migration inhibitory factor (MIF) recovered from acute bacterial infection more efficiently than wild-type control mice." (PMID 20361053, 2010). "With regard to bacterial infection, the role of MIF has been first studied in abdominal sepsis caused by either intraperitoneal injection of E. coli or CLP." (PMID 20169062, 2010). "In the presence of bacterial infection for example, inflammation is normally triggered, and the subsequent release of MIF allows for prolonged inflammation through the release of other pro-inflammatory cytokines like TNF-α, IL-1β, IL-6, IL-8, IL-2, and IFN-γ." (PMID 26741693, 2016). "Macrophage migration inhibitory factor (MIF) is a proinflammatory cytokine that has emerged as an important mediator of the host defense in severe bacterial infections." (PMID 20169062, 2010). "MIF plays a complex role in the host response to bacterial infections." (PMID 38275363, 2023). "Other SNPs involved in the bacterial infection might be relevant in BM e.g. macrophage migration inhibitory factor (MIF) Toll-interleukin 1 receptor domain containing adaptor protein (TIRAP) and complement mediated inflammation." (PMID 22662111, 2012). "Taken together, these findings indicate that MIF has an important role in bacterial infections." (PMID 23319831, 2012). "The deletion of p115 from monocytes/macrophages reduces the release of MIF but no other cytokines following inflammatory stimulation or intracellular bacterial infection." (PMID 37283810, 2023). "To examine if bacterial infections could be influencing the release of the inflammatory and anti-inflammatory cytokines, we measured levels of the LPS, FABP2, MIF and sCD14 molecules." (PMID 26814478, 2016).
neurodegenerative disease (16 papers, 2014 to 2025). A disorder of the central nervous system characterized by gradual and progressive loss of neural tissue and neurologic function. "Functioning as an ATP‐independent chaperone, MIF prevents the misfolding of mutant superoxide dismutase, a process whose pathological accumulation is implicated in the progression of neurodegenerative diseases." (PMID 41323117, 2025). "Several protein groups associated with aging and neurodegenerative diseases including apolipoprotein E (ApoE), S100B, Sod1, Sod2, huntingtin (Htt), macrophage migration inhibitory factor (Mif), α-Synuclein (Snca) were modulated by either drug treatment or the behavioural training per se." (PMID 34907284, 2021). "Therefore, they suggested that MIF dysfunction caused by NO might be involved in the loss of neuronal viability associated with neurodegenerative diseases, such as PD." (PMID 32344747, 2020). "MIF was previously associated with both Aβ and tau pathology in AD, but both pathogenic and protective roles have been found in different neurodegenerative diseases for MIF and its homologue DDT." (PMID 36829875, 2023). "This review highlighted the involvement of MIF in neurodegenerative diseases, in particular in ALS, PD, and HD." (PMID 32344747, 2020). "During the last decades, the study of the potential role of MIF in neurodegenerative diseases has attracted increasing interest because of its ability to modulate various functions both in physiological and pathological conditions of the CNS." (PMID 32344747, 2020). "In this review we highlighted current concepts on the physiological and physiopathological role of MIF in the regulation of CNS processes and functions and the possible influence it plays on these neurodegenerative diseases." (PMID 32344747, 2020). "MIF is an established species in the brain with suggested protective roles against neurodegenerative disease." (PMID 24447830, 2014). "This might be combined with drugs that stop the loss of PNN or block the interaction of MIF with its known receptor (CD74) for a therapeutic strategy to treat ALS and other neurodegenerative diseases." (PMID 33339362, 2020). "However, because of its pleiotropic biological functions, during the last decades, many studies have investigated the involvement of MIF in neurodegenerative diseases." (PMID 32344747, 2020). "Indeed, AIF and its associated nuclease, macrophage migration inhibitory factor (MIF) (rechristened as PARP-1-dependent AIF-associated nuclease or PAAN), are key players in “parthanatos”, a regulated necrosis implicated in neurodegenerative disease." (PMID 36752525, 2023). "Conversely, if MIF exerts a pathogenetic action, specific MIF antagonists, such as anti-MIF monoclonal antibodies or small molecule inhibitors, could represent a valuable possibility of complementary therapy in certain cases and phases of these neurodegenerative diseases." (PMID 32344747, 2020).
immune diseases (14 papers, 2009 to 2025). "Macrophage migration inhibitory factor (MIF) is a multifunctional cytokine associated with several inflammatory and immune diseases." (PMID 40016840, 2025). "MIF is a pleiotropic molecule and a key mediator of many immune processes, and has been implicated to exacerbate inflammation in several immune disorders." (PMID 29095944, 2017). "Several studies proposed that MIF polymorphism increased the risk of immune disease." (PMID 28507475, 2017). "Later investigations disclosed that MIF acts as a pro-inflammatory factor., which has important roles in various chronic inflammatory diseases and immune disorders, including UC." (PMID 38288119, 2023). "Macrophage migration inhibitory factor (MIF) is pleiotropic cytokine that has multiple effects in many inflammatory and immune diseases." (PMID 30968541, 2019). "Macrophage migration inhibitory factor (MIF) plays a pivotal role in inflammatory and immune diseases and in inflammatory-like reproductive events as ovulation, menstrual cycle, and early placentation." (PMID 22007254, 2012). "Using standard immunization protocols, we were able to induce strong antibody responses in this strain against highly conserved human antigen MIF or mouse self-antigen TNF-alpha before the onset of auto-immune disease." (PMID 19564921, 2009). "In this context, we have been working under the hypothesis that the positive Nef-mediated modulation of CD74 in HIV-infected cells plus MIF overexpression play a relevant role in HIV-mediated immune dysfunction and immunopathogenesis." (PMID 36298774, 2022). "MIF levels rise during infectious, inflammatory, and auto-immune diseases." (PMID 35115654, 2022).
neurological diseases (9 papers, 2009 to 2024). "Of note, different approaches to modulating MIF-dependent pathways are now in advanced clinical testing, including neurologic disorders." (PMID 38178143, 2024). "MIF is recently defined as one of DAMPs that mediates multiple neurological diseases and severity of SCI." (PMID 37334735, 2023). "A recent review concluded that the role of MIF in neurological disorders is controversial and depends on the pathophysiological context and/or cellular microenvironment." (PMID 35324982, 2022). "All the results indicated that the role of MIF in nervous system disease is still controversial and need further study." (PMID 32964038, 2020).
adenocarcinoma (8 papers, 2005 to 2024). A common cancer characterized by the presence of malignant glandular cells. "Recent studies have also highlighted MIF’s presence in exosomes released from adenocarcinoma cells, proposing a novel mechanism for MIF’s extracellular interactions." (PMID 39337534, 2024). "A heatmap of the MIF signalling pathways between different cell types showed that endothelial, club, adenocarcinoma stem‐like, mast, myeloid, neutrophils, T and B cells transmitted the MIF signals to other cells." (PMID 37784249, 2023). "Vecchio and colleagues have indicated the existence of association between level of MIF factor and cellular differentiation in untreated PCa, showing that MIF expression was stronger in low-grade adenocarcinoma (GS≤6) than in high-grade adenocarcinoma (GS≥7)." (PMID 34157052, 2021). "In contrast, neoplastic cells from well-differentiated polypoid adenocarcinoma showed mild MIF immunostaining, while inflammatory cells, particularly macrophages, showed stronger immunoreactivity." (PMID 31360118, 2019). "Only matched samples of benign and adenocarcinoma tissue were included in the final analyses (MIF in situ, n = 20; MIF IHC analysis, n = 20; CD74 IHC, n = 18)." (PMID 16000172, 2005). "MIF knockdown decreased LPA-mediated proliferation of HCT116 human adenocarcinoma cells without altering the basal proliferation rates." (PMID 26352431, 2015).
brain diseases (6 papers, 2009 to 2024). "A novel therapeutic approach utilizing our DRQ construct to inhibit dual effects of MIF and D-DT signaling has the potential to treat all progressive brain diseases involving CD74-dependent neuroinflammatory pathways." (PMID 38178143, 2024). "This review focuses on MIF research and actions in progressive brain diseases such as MS, AD and GBM." (PMID 38178143, 2024). "MIF can also induce neural stem/progenitor cells proliferation and maintenance for the treatment of degenerative brain disorders." (PMID 32964038, 2020). "Furthermore, inhibition of MIF protected mice from brain disease due to West Nile virus or autoimmune encephalomyelitis, further suggesting that MIF plays a pathophysiological role in CNS infection." (PMID 19558639, 2009).